PIWIL4 (piwi like RNA-mediated gene silencing 4)
Diseases named in the same sentence as PIWIL4 in open-access papers (continued):
Sharing a sentence is not in itself a finding about the gene and the disease.
tumor (26 papers, 2010 to 2025). "High expression of PIWIL4 is also reported to be associated with the initiation and progression of tumor." (PMID 36324572, 2022). "In contrast, downregulated expression of PIWIL1, PIWIL2, and PIWIL4 genes was observed in high-stage RCC tumour samples and was associated with worse overall survival (OS) of patients." (PMID 35204687, 2022). "In the multivariate analysis, low PIWIL4 expression remained statistically significant for a higher risk of progression (HR = 2.036; 95% CI: 1.025–4.044; p = 0.042) together with tumor size (HR = 3.095; 95% CI: 1.237–7.744; p = 0.016)." (PMID 32357464, 2020). "Significant positive associations were observed between the tumor group showing PIWIL4 underexpression and HR+ status (p = 0.0002) and HR+ ERBB2+ molecular subtype (p = 0.0037)." (PMID 33008024, 2020). "It is suggested that EIF2C2-4 and PIWIL4 are associated with tumor progression to advanced stage and may promote tumor invasion." (PMID 20146808, 2010). "PIWIL4 levels were directly proportional to tumor recurrence time (TTR) (p = 0.048) and overall survival (OS)." (PMID 36915129, 2023). "The expression of PIWIL1-4 genes was analysed in paired ccRCC-normal tissue samples, and higher expression of PIWIL4 in tumour tissue was observed." (PMID 35204687, 2022). "Higher PIWIL3 or PIWIL4 downregulation in both tumor cell lines was achieved between the fifth/sixth days compared with the second day obtained in the non-tumor cell line." (PMID 32357464, 2020). "Remarkably, we observed that PIWIL3 and/or PIWIL4 knockdown dropped drastically the number and diameter of spheres of tumor cell line RWP1 (p < 0.001)." (PMID 32357464, 2020). "Our findings support PIWIL3 and PIWIL4 as crucial factors in the regulation of cell motility, stem cell maintenance and drug resistance both in tumor and healthy pancreatic cells." (PMID 32357464, 2020). "Our experiments, designed to evaluate cell motility, chemoresistance and undifferentiated phenotype, revealed that the effect observed after PIWIL3 and/or PIWIL4 downregulation in tumor cells were also shown by the non-tumor cell line." (PMID 32357464, 2020). "In contrast, PIWIL3 and PIWIL4 showed overexpression in almost all tumor-derived cell lines, and in the non-tumor pancreatic cell line compared to control." (PMID 32357464, 2020). "Here, we observed how PIWIL3 and PIWIL4 knockdown decreased motility of both tumor and normal cells through a mesenchymal arrest in favor of the epithelial phenotype." (PMID 32357464, 2020). "Only tumor size higher than 2 cm emerged as statistically significant together with low PIWIL4 expression in Cox multivariate analysis for progression-free survival." (PMID 32357464, 2020). "Following with functional experiments with PIWIL3 and/or PIWIL4 downregulation, we evaluated the ability of both tumor and non-tumor pancreatic derived cell lines to form pancreatic spheres in stem cell enrichment culture media." (PMID 32357464, 2020). "We also observed that PIWIL3 and/or PIWIL4 silencing impaired undifferentiated phenotype and enhanced drug toxicity in both tumor- and non-tumor-derived cell lines." (PMID 32357464, 2020). "PIWIL1, PIWIL2 and PIWIL4 were also localized within the nucleus and the cytoplasm of several subtypes of cells belonging to the tumor microenvironment such as immune cells, endothelial cells and fibroblasts." (PMID 33008024, 2020). "On the other hand, PIWIL3 and PIWIL4 showed higher protein levels and a differential expression pattern throughout cell lines, which includes a non-tumor cell line." (PMID 32357464, 2020). "PIWIL1, PIWIL2, PIWIL3 and PIWIL4 were all deregulated with a dissociated profile: PIWIL1 and PIWIL3 had an abnormal emergent expression and the remaining PIWIL2 and PIWIL4 were variably downregulated in tumor tissues at RNA and protein levels." (PMID 33008024, 2020). "Here, we found that maximum PIWIL3 or PIWIL4 downregulation was achieved later in both tumor cell lines than in non-tumor cell line." (PMID 32357464, 2020).
tumor (continued). "PIWIL4 was downregulated in tumor tissues and patients with lower levels of PIWIL4 had a shorter TTR and OS than others." (PMID 31890151, 2019). "The differences in the expression and location of Piwil2 and Piwil4 in tumor cells were explored, and the influence of such differences on the long-term survival rate of HCC was studied using Kaplan-Meier survival curve and log-rank test." (PMID 27894076, 2017). "Comparison with normal breast tissues revealed that two genes (PIWIL1 and PIWIL3) were up-regulated and the remaining two (PIWIL2 and PIWIL4) were down-regulated in tumor tissues." (PMID 27177224, 2016). "Recently it was reported that miR-384 exerted tumor-suppressive functions by binding to the 3'UTR of PIWIL4." (PMID 27769041, 2016). "Piwil1 was only detected in the cytoplasm of tumor cells in few cases, while Piwil2 and Piwil4 were detected in most of the cases." (PMID 27329591, 2016). "PIWIL2 and PIWIL4 were both expressed in all samples – both in the embryonic and the adult normal and tumor tissue." (PMID 25742785, 2015). "PIWIL2 and 4 were downregulated in tumor tissue in comparison to the normal tissue (p < 0.001) and the patients with lower levels of PIWIL4 had shorter TTR (p = 0.048) and OS (p = 0.033)." (PMID 25742785, 2015). "Both PIWIL2 and PIWIL4 were also expressed in tumor and normal tissue, indicating that the secondary pathway is not inactivated in adult tissue." (PMID 25742785, 2015). "Both PIWIL2 and PIWIL4 were significantly downregulated in tumor tissue compared to normal tissue (p < 0.001)." (PMID 25742785, 2015). "In the present study, we found the positive correlation of EIF2C2, EIF2C3, EIF2C4 and PIWIL4 with tumor distant metastasis." (PMID 20146808, 2010). "In addition, compared with normal tissues, the expression of PIWIL2 and PIWIL4 was downregulated in tumor tissues." (PMID 36915129, 2023). "Finally, piR-162725 was significantly downregulated in the RWP1 tumour cell line after PIWIL3 silencing compared to the same tumour cell line after PIWIL4 silencing (Log2 fold change = −24.44; adjusted p-value = 1.63 × 10−5)." (PMID 36555927, 2022). "PIWIL3 and PIWIL4 were located both in the nucleus and the cytoplasm of tumor cells." (PMID 33008024, 2020). "Through bioinformatics analysis, we found the expressions of PIWIL1 and PIWIL4 were increased in GC tumour tissues as compared to the normal gastric mucosa tissues whereas the high expression of PIWIL4 in GC tumour tissues was correlation with poor OS in GC patients." (PMID 33169519, 2020). "Indeed, PIWIL3 and/or PIWIL4 silencing overcame Gemcitabine resistance of the non-tumor cell line (p < 0.001), and significantly increased the other treatment effects (p = 0.003 for Nab-Paclitaxel; p = 0.001 for Gemcitabine + Nab-Paclitaxel)." (PMID 32357464, 2020). "Since PIWIL3 and PIWIL4 are expressed in the immortalized non-tumor pancreatic cell line, we cannot conclude that PIWIL3 or PIWIL4 could act as an oncogene." (PMID 32357464, 2020). "As molecular chaperones, Piwil2/Piwil4 are co-expressed and localized in the tumor tissue." (PMID 27894076, 2017). "The co-expression and localization of molecular chaperone Piwil2/Piwil4 in the tumor tissue could be used as an indicator for tumor prognosis." (PMID 27894076, 2017). "Interestingly, PIWIL2 and PIWIL4 were expressed at significantly lower levels in tumor than in paired normal tissue (p < 0.001)." (PMID 25742785, 2015). "The expression of EIF2C2-4 and PIWIL4 appeared significantly increased in advanced tumors with distant metastasis, suggesting it may promote tumor invasion." (PMID 20146808, 2010). "The expression of EIF2C2-4 and PIWIL4 appears increased in advanced tumors with distant metastasis, suggesting it may promote tumor invasion." (PMID 20146808, 2010). "Therefore, the role of PIWIL3 and PIWIL4 in tumor initiation and development remains still unclear." (PMID 32357464, 2020).
tumor (continued). "Therefore, it could be deduced that the difference in the localization of Piwil2 and Piwil4 in tumor cells could be related to the malignant degree or prognostic phenotype of HCC." (PMID 27894076, 2017). "Specifically, PIWIL4, SATB1, GSE1, NCOR1, SAP30L, ATM, and BMI1 were significantly downregulated in tumor tissues relative to normal controls, while BUB1, CHEK1, MASTL, DNAJC2, UBE2D1, and SSRP1 showed pronounced upregulation." (PMID 41208974, 2025). "We have also discovered the link between PIWIL3 and PIWIL4 and epithelial-to-mesenchymal transition (EMT) and tumour cell dedifferentiation status and chemoresistance." (PMID 36555927, 2022). "We investigated the correlation of PIWIL4 and SUPT5H with the tumour microenvironment, and the results suggested that the high riskScore was positively related to the enrichment of resting natural killer (NK) cells and activated memory CD4 + T cells." (PMID 34876138, 2021). "Univariate and multivariate regression analyses identified two independently survival-related DE-RBPs, namely PIWIL4 and SUPT5H, with the coefficients being less than 0, suggesting that they were key protective factors in tumour progression." (PMID 34876138, 2021). "In tumor tissue, PIWIL1 expression was detected in eleven patients (15.5%), PIWIL2 in 66 (93%), PIWIL3 in five (7%) and PIWIL4 in 60 (84.5%)." (PMID 25742785, 2015). "Furthermore, we found a large number of differentially expressed piRNAs when comparing tumour cell lines (RWP1 and PL45) downregulated for PIWIL3 or PIWIL4 against IPMN samples (n = 94) or against human PDAC samples (n = 22)." (PMID 36555927, 2022). "The expression pattern of PIWIL4 was limited to cytoplasm and cell membrane of tumor cells, and no positive nuclear staining was found." (PMID 32357464, 2020). "Subsequently, functional experiments with PIWIL3 and/or PIWIL4 knockdown revealed a decrease in the motility ratio of tumor and non-tumor cell lines through downregulation of mesenchymal factors in pro of epithelial factors." (PMID 32357464, 2020). "Interestingly, this fact was not only observed in tumor cell lines but also in the normal cell line, which also decreased its motility after PIWIL3 and/or PIWIL4 downregulation." (PMID 32357464, 2020). "To the best of our knowledge, we have described for the first time the implication of PIWIL3 and PIWIL4 in cell motility through EMT modulation of tumor and non-tumor pancreatic cells." (PMID 32357464, 2020). "Here, we show a differential expression in tumor and non-tumor cell lines of PIWIL3 and PIWIL4." (PMID 32357464, 2020). "The transformation from the negative expression of Piwil2/Piwil4 protein in the cytoplasm to the positive expression in the nucleus indicated that the tumor became more malignant." (PMID 27894076, 2017). "Notably, we validated that PIWIL4 and SUPT5H expression pattern in ICC using the laboratory experiments, which indicated that both PIWIL4 and SUPT5H might involve tumour progression of ICC." (PMID 34876138, 2021). "We identified immunostaining of tumor cells with anti-PIWIL1 antibodies in 34,6% of IBCs (n = 52) and anti-PIWIL3 antibodies in 8% of IBCs (n = 12) and absence or slight staining with anti-PIWIL2 antibody in 48,3% of IBCs (n = 67) and anti-PIWIL4 antibody in 48,6% of IBCs (n = 73)." (PMID 33008024, 2020). "By analyzing tumor microenvironment, we could observe that IBCs with PIWIL2 underexpression (but not PIWIL4 underexpression) were significantly correlated with increased immune cytotoxic CD8+ response (p = 0.000029)." (PMID 33008024, 2020). "PIWIL2/PIWIL4 co-expression and localization in HCC may be useful as an indicator for tumor prognosis, as the transformation of negative to positive cytoplasmic PIWIL2/PIWIL4 expression indicates that tumors are in the precancerous period or in the initial stage of tumorigenesis." (PMID 31399034, 2019).
benign tumors (2 papers, 2014 to 2020). "However, the expression of PIWIL2 and PIWIL4 are significantly lower in benign tumors compared to normal ovarian tissue, suggesting an alteration of gene expression during the progression of EOC." (PMID 24932571, 2014). "Most tumors had no PIWIL3 expression whereas PIWIL4 had significantly lower expression in early stage HGSOC samples but not late stage when compared to benign tumors." (PMID 33374923, 2020).
pancreas (1 paper, 2020). "A second profile of expression associated variable PIWIL2 and PIWIL4 genes downregulation, an aberrant level of PIWIL1 and absence of PIWIL3 expression observed in anal canal, head and neck, cervix, skin, kidney and pancreas tumors." (PMID 33008024, 2020).
PIWIL4 also shares sentences with these, for which no sentence is quoted: gastric cancer (4 papers); seminoma (3); cardiac hypertrophy (2); infection (2); amyotrophic lateral sclerosis (1); anemia (1); attention deficit-hyperactivity disorder (1); depression (1); embryonal carcinoma (1); erythroleukemia (1); glioblastoma (1); head and neck squamous cell carcinoma (1); influenza (1); lung adenocarcinoma (1); melanoma (1); myelodysplastic syndrome (1); Obesity (1); retinoblastoma (1); rheumatoid arthritis (1); soft tissue sarcoma (1); Streptococcus pneumonia (1); testicular germ cell tumor (1); viral infection (1).